CDK2 (cyclin dependent kinase 2)
Diseases named in the same sentence as CDK2 in open-access papers (continued):
Sharing a sentence is not in itself a finding about the gene and the disease.
tumor (continued). "This is the first study to demonstrate that pharmacological inhibition of CDK2/9 or 7 can inhibit tumour growth in gliomasphere cultures regardless of their driver oncoprotein or classification as either primary or recurrent." (PMID 34344865, 2021). "As CDK2 expression was aberrant in poorly differentiated G3 tumours, it can be speculated that the CCNE1-driven HCC progression may depend on CDK2-expression levels at a late stage." (PMID 34830835, 2021). "Moreover, the cell cycle is an essential factor of cell growth; the cell cycle is regulated by complexes of cyclins and cyclin-dependent kinases during cell division, Cyclin D1, CDK1, CDK2, and CDK4 are often upregulated in tumor cells." (PMID 33953676, 2021). "Notably, tumor sample analysis showed that RB1 protein abundance was slightly increased, while protein levels of CDK6, cyclin D3, cyclin E1, cyclin D1, SKP2, and CDK2 were significantly decreased in the combination treatment group." (PMID 34508104, 2021). "Consistent with the results of in vitro experiments, miR-30b-3p overexpression could promote tumor progression by decreasing RHOB and increasing Ki-67, CDK2, and CDK6." (PMID 33408780, 2021). "Decreased levels of miR-320a in CAF-derived exosomes promote cell proliferation, migration, and metastasis; loss of miR-320a leads to de-repression of its target PBX3, activating MAPK pathway and up-regulation of CDK2 and MMP2; in vivo, miR-320a overexpression suppresses tumor growth and metastasis." (PMID 32957712, 2020). "EZH2-mediated PRC2 activation contributes to the transcriptional silencing of tumor suppressor genes, leading to the activation of NOTCH, JAK-STAT, or β-catenin signaling pathways and upregulation of cell cycle genes, such as CDK2, CDK4, and CCND1." (PMID 33121524, 2020). "Proteins from transplanted tumor tissues were extracted for Western blot analysis, and the results displayed that levels of FTO, MYC, CDK2, CDK4, Ki-67, PCNA and Bcl-2 proteins in miR-96 antagomir group were downregulated, while AMPKα2 and Bax proteins were raised." (PMID 33183350, 2020). "Furthermore, safranal-treated tumor tissues exhibited a reduction in Skp2, E2F1, NF-κB p65, p-IκBα (Ser32), c-MYC, p-Rb (Ser807), CDK4, CDK6, and CDK2 and an elevation of p27 and p21 protein levels." (PMID 33392189, 2020). "In addition, SU9516 is a selective inhibitor of cyclin-dependent kinase 2 (CDK2), which can inhibit the proliferation of various tumor cells." (PMID 33396550, 2020). "In agreement with the in vitro results, immunoblotting analysis of tumor homogenates showed that shRNA-TTN-AS1 treatment led to downregulation of NRP-1, cyclin E, and CDK2, and upregulation of p27; while antagomiR-320a counteracted the effects of shRNA-TTN-AS1." (PMID 32801339, 2020). "However, in the CGC tumour tissues, the genes most frequently showing CNGs were CDKN1B (42.9%), H3F3A (23.8%), CDK2 (14.3%), NFKBIA (14.3%), and VEGFA (14.3%)." (PMID 30989433, 2019). "The results indicate that NT1721 might, at least partially, decrease the cell cycle progression and thus tumor growth through CCNE1 and CDK2 downregulation." (PMID 31661013, 2019). "Moreover, CDK2 and SIRT1 expression in the tumor pieces of these patients tended to directly, while CDKN2A inversely, be correlated with GOAT urine levels." (PMID 31766715, 2019). "Interestingly, TCGA data analysis revealed that the CDK1, CDK2, CCNB2, and SKP2 genes were significantly upregulated, but the SKP1 gene was downregulated in tumor samples compared with normal samples." (PMID 31717435, 2019).
tumor (continued). "The p27 protein has been suggested to be a tumor suppressor with a haploinsufficiency phenotype, and in the absence of p27, CDK2 activity was increased." (PMID 30642385, 2019). "Alterations to cyclin D1, CDK1, CDK2, CDK4 and p16, which regulate the cell cycle, led us to speculate whether ABHD11‐AS1 affects tumour progression by regulating the protein expression of factors linked to the cell cycle." (PMID 29799152, 2018). "miR-3140 suppresses other tumor promoting genes, such as EGFR and CDK2, via 3′UTR." (PMID 29540837, 2018). "Moreover, 17 cell cycle markers, including CDK2, CCND1 and CDKN1A, 20 cellular growth and proliferation markers, and other biomarkers for NB or other tumours, were also identified." (PMID 28246384, 2017). "Interestingly, many of these genes are known to be involved in cell-cycle function (CDK2, CDK6, CCNB1, CEP55, CENPF), transcriptional regulation/tumor suppression (FOXO3, TOP2A), DNA-damage response (ASPM, XRCC4), and tumor progression (CYR61, MACC1, CXCR4)." (PMID 28482906, 2017). "We have also shown that CDK2 inhibition can block non-canonical Smad3 phosphorylation, resulting in restoration of the tumor-suppressor role of Smad3 in TNBC." (PMID 29137393, 2017). "This is the subject of ongoing study in our group, building from prior work showing that CDK2 inhibition of non-canonical Smad 3 phosphorylation enhanced the anti-tumor activity of taxane treatment in TNBC, both in vitro and in vivo." (PMID 29137393, 2017). "Together, these results showed that the inhibition of CDK2 and CDK9 activity by dinaciclib could block NB tumor development and induce tumor cell death in TH-MYCN transgenic mouse model." (PMID 27378523, 2016). "Collectively, these results showed that the inhibition of CDK2 and CDK9 activity by dinaciclib could block NB growth and induce tumor cell death in vivo." (PMID 27378523, 2016). "In combination with the observation of a lack of CDK2 dysregulation for OP vs O, this pattern suggests an overall environment for increased tumor progression for proton irradiated adolescent hosts due to overall increased cell cycling." (PMID 26253138, 2015). "In addition, cell cycle markers, for instance, cyclin A2, Cyclin Dependent Kinase-2, 6 and MAPK1, 14, 10 promote the tumour progression whereas caspase 3 inhibits the tumour progression." (PMID 26385094, 2015). "CDK1 and CDK2, two cell cycle regulatory protein kinases that play important roles in cell cycle transitions, have been reported to phosphorylate FOXO1 and attenuate its tumor suppressor function." (PMID 25472505, 2014). "The antisense-mediated knockdown of KAP in Huh-7 cells decreased cell proliferation, reduced the colony-forming ability of the cells, interfered with cell cycle progression and suppressed xenograft tumor formation, partly through enhanced KAP and Cdk2 interaction." (PMID 23292002, 2013). "While mice with at least one functional copy of Cdk2 consistently developed mammary gland tumours, Cdk2-/- mice did not develop tumours through 24 months." (PMID 22433433, 2012). "Erk1/2 inhibitor pretreatment or incubation prevents this MICA decrease, while up-regulating key cell cycle related molecules such as CDK2, CDK4 and Cyclin D1, as well as apoptosis related molecules making resistant tumor cells now vulnerable to γδ T cell-mediated lysis." (PMID 21935360, 2011). "Any effectors that alter the balance of p27 and CDK2, ERK and p38 may have profound consequences for tumor growth and survival." (PMID 21079779, 2010). "In addition, recent works have identified as MITF transcriptional targets genes such as the CDK2, the hipoxia induced factor HIF1A and the hepatocyte growth factor receptor MET, all of them presenting functions that contribute to tumor development." (PMID 18211678, 2008).
tumor (continued). "To determine the impact of 4HYP-modified collagen matrix produced by P4HA2-depleted cells on tumor cell quiescence, we generated decellularized matrix scaffolds from D-HEp3 nodules or P4HA2-depleted D-HEp3 awakened tumors and seeded D-HEp3 cells expressing a CDK2 biosensor onto them." (PMID 40671813, 2025). "This confirms that prolonged CDK2 inhibition in vivo can exert sustained control of CCNE1-amplified tumors, and that rebound compensation by CDK4/6 is not present to a level sufficient to significantly restore Rb phosphorylation, cyclin A2 expression, or tumor growth." (PMID 38047585, 2024). "When CDK2 and EZH2 was recovered in POU4F1‐KO BLBC cells, ERα was re‐expressed and the downstream signaling was re‐activated, resulting in the conversion between basal‐like and luminal‐like phenotype, suggesting the regulatory role of cell cycle in tumor cell identity." (PMID 38491910, 2024). "Consequently, combined CDK2 and AKT inhibition may have synergistic anti-tumor activity against CCNE1-amplified tumors and hold promise for clinical development." (PMID 38894867, 2024). "In addition, another investigation has demonstrated the m6A-dependent role of YTHDF1 in regulating the translation efficiency of cyclin-dependent kinase 2 (CDK2), CDK4, and cyclin D1 (CCND1), thereby exerting control of NSCLC cell proliferation and xenograft tumor formation." (PMID 39342406, 2024). "The interaction network showed that FOXM1 was closely correlated with those proteins who are involved in the cell cycle, such as cyclin-dependent kinase 1 (CDK1), CDK2, Cyclin B1 (CCNB1), as well as CCNB2, indicating FOXM1 may act as an important regulator of the tumor cell cycle." (PMID 37159818, 2023). "Selective CDK2 inhibitors have not been widely used in tumor research." (PMID 37865750, 2023). "miR-154-5p acts as tumor suppressor in osteosarcoma and its upregulation inhibits the proliferation, migration and invasion in vitro as well as in-vivo tumor growth via the dysregulation in the pro-apoptotic proteins’ expression and the cell cycle regulators such as E2F5, Cyclin E1 and CDK2." (PMID 35755302, 2022). "This could be explained by the increased activation of CDK2 in the process of palbociclib resistance, and tumor metabolism not completely reflecting the true condition of CDK4/6." (PMID 35711853, 2022). "In addition, the resected tumor tissues were stained with H&E, Ki67, TUNEL and CDK2." (PMID 36235266, 2022). "Importantly, subsequent in vitro kinase activity assays revealed that one out of three HCCs did not exhibit CDK2 kinase activity above background levels despite strong tumour proliferation (see sample #243)." (PMID 34830835, 2021). "Importantly, the deletion of Ccne1, but not of Cdk2, significantly reduced the number of Ki67-positive cells in tumours." (PMID 34830835, 2021). "Interestingly, any resistance observed with the CDK2 inhibitors is believed to be due to the upregulation of CDK2 itself and selection of pre-existing polyploid cells, frequently observed in CCNE1-amplified tumor cell populations." (PMID 33182737, 2020). "We found here that CDK2 was downregulated in the primary NFPA group, suggesting that this is a marker for NFPA development; on the other hand, CDK2 expression was elevated in the invasion and recurrence groups, implying that a high CDK2 level contributes to tumor progression." (PMID 31223310, 2019). "Thus, downregulation of CDK2 and EGFR may partially contribute to miR-3140-mediated suppression of tumor cell growth." (PMID 29540837, 2018).
tumor (continued). "In the present study, the CDK1/2/9 inhibitor AZD5438 exerted significant tumor inhibition in two PDX models with high copy number of CCNE1, and we also found that AZD5438 exerted antitumor activity by inhibiting the expression of CDK2, CCNE1, and phosphorylated retinoblastoma (pRb)." (PMID 29433585, 2018). "Moreover, having been originally developed as anticancer agents that do not interfere with the tumor-killing ability of cisplatin, CDK2 inhibitors are superior to many other benchmark compounds in preclinical and clinical trials against ototoxicity." (PMID 29514916, 2018). "Direct suppression of BRD4-NUT and concurrent downregulation of other tumor promoting genes such as EGFR and CDK2 by miR-3140 may potentially overcome resistance to BET inhibitors in NMC cells, although further studies are needed to clarify the acquired resistance of BET inhibitiors." (PMID 29540837, 2018). "Si-CDK2 significantly reduced tumor cell growth in MIAPaCa2 cells, but not in Panc1 cells." (PMID 29540837, 2018). "While this may be due to non-optimal patient stratification or limited tumor uptake, CDK2-inhibitors generally suffer from specificity problems." (PMID 28665315, 2017). "Substantial reduction of tumour growth was observed in p16/p21-DKO mice but not in mice lacking either p16Ink4a or p21Cip1/Waf1 (single KO mice), suggesting that both CDK2 and CDK4 associate with this transcription factor in a complementary fashion." (PMID 29234059, 2017). "Thus, whereas CDK2 gene deletion did not affect tumour cell growth, R50 cells have lower proliferative fitness both in vitro and in vivo." (PMID 29222471, 2017). "This suggests that whereas expression levels of cdk2 and cyclin E do not increase with tumor mass, activity of this cdk/cyclin complex, resulting in phosphorylation and inactivation of Rb, may increase in larger tumors." (PMID 27077880, 2016). "Indeed, the pRb/Rb was significantly lower in these cells than in tumor cells, supporting that cyclin E/Cdk2 complex was not active in MCF10A." (PMID 25941117, 2015). "Since cdk2/cyclin A reduction and growth inhibition in Cakires after application with VPA was accompanied by acetylation of histone H3 and H4, epigenetic modification might be involved in the anti-tumor effect." (PMID 24935000, 2014). "Further studies using chemical bioinformatics and biochemical assays suggested that the lead compound selected by zebrafish assay had a higher specificity to CDK2 kinase inhibition and it also reduced tumor cell proliferation in vivo without significant toxicity to xenograft mouse hosts." (PMID 19194508, 2009). "Also, inhibition of CDK2 activity through expression of p27 Kip1, dominant-negative CDK2, antisense oligonucleotides or siRNA did not have an effect on growth of several tumor cell lines." (PMID 17083724, 2006). "However, combining CDK2 inhibition with EMP3 silencing sufficiently compromises the viability of NCH1425 GSCs, highlighting how multiple insults may be required to target stem-like tumor cells." (PMID 37936247, 2023). "In addition to inhibition of apoptosis, activated NF-κB may control cell cycle progression by regulating the expression of important cell cycle regulatory proteins such as cyclin D1 and cyclin dependent kinase 2 (CDK2), further contributing to the tumour growth." (PMID 24416253, 2014). "In these tumours, cell cycle progression occurs in the presence of both CDK inhibitors, suggesting that the CDK7i is acting via the same pathway as palbociclib where CDK2/4/6 inhibition are no longer relevant in palbociclib-insensitive cells." (PMID 37190140, 2023).
tumor (continued). "The analysis of the TCGA GBM dataset revealed increased mRNA expression of CDK2, 7, and 9 in GBM patient tumours compared to non-tumour tissue." (PMID 34344865, 2021). "We saw that the inhibitory effect was mimicked by suppressing CDK2 by using specific shRNAs and further found that neither TrkA nor CDK9 was involved in the mechanisms of tumor cell suppression." (PMID 29511348, 2018). "The cell cycle regulating proteins cdk1, cdk2 (not in KTC-26), cdk4 (not in A498), cyclin A and cyclin B were all down-regulated in the tumour cells when treated for 24 hrs with sunitinib." (PMID 25444514, 2015). "On the other hand, we have not observed differences in cyclin E, CDK2 and CDK4 levels between catalase-treated and non-treated cells and between non-tumor and tumor cells." (PMID 22970236, 2012). "Microarray analysis revealed the CDKN2A and CDKN1A genes to be significantly repressed in all tumour types vs controls while the CDK2 gene was upregulated in the all tumours vs controls and CDK6 was also upregulated in GH-secreting tumours vs controls (data not shown)." (PMID 28649092, 2017). "The tumor growths of Cdk2-/- and Cdk2-/–CD39 overexpression cells were similar and slower than those of WT MCS205 cells, which suggest that their differences in ATP release might not be responsible for their differential tumor growth rates." (PMID 40557162, 2025). "However, the fascinating observation of our study is that the hub genes including CDK1, CDK2, CCNB1, and HDAC1 and common genes including E2F3 identified in Rb tissues are well-known oncogenes that trigger cell cycle progression in tumor cells in the absence of RB1 gene." (PMID 35359459, 2022). "In addition, gains in cyclin-dependent kinase 2 (CDK2) and erb-b2 receptor tyrosine kinase 3 (ERBB3) were found only in recurrent lesions (37.5% and 37.5%, respectively) but not in the corresponding primary tumor controls." (PMID 36135044, 2022). "The opposing relationships between CDK2/CDK3 (negative) and CDK5 (positive) with regulatory T cell populations suggest that selective CDK inhibition could serve dual therapeutic functions—blocking tumour proliferation while simultaneously enhancing anti‐tumour immunity." (PMID 40682474, 2025). "Importantly, tumor cells have numerous mechanisms of resistance to CDK4/6 inhibitors at their disposal, which are both cell cycle specific (e.g., CCNE amplification and CDK2 hyperactivation) and independent of the cell cycle (e.g., activation of PI3K/AKT/mTOR signaling)." (PMID 32344731, 2020).